C15orf62 (chromosome 15 open reading frame 62)
Synonyms: LOC643338
Tractability: Antibody: its Gene Ontology location is reachable by antibodies, with medium confidence.
Gene: Protein-coding gene on chromosome 15 (40,769,980 to 40,772,449, forward strand). Ensembl gene ENSG00000188277.
Subcellular location: Mitochondrion
Gene Ontology:
Molecular function: small GTPase binding
Biological process: positive regulation of actin filament polymerization; positive regulation of pseudopodium assembly; regulation of cell shape; Rho protein signal transduction
Cellular component: mitochondrion; cytoplasm; cytoskeleton; plasma membrane
Genetic constraint (gnomAD): Loss-of-function variants: 11 observed, 13.28 expected, observed/expected ratio (o/e) 0.83, 90% interval 0.52 to 1.37. The upper end of that interval is the gene's LOEUF score, 1.37, which puts it in group 5 of 6, group 1 being the genes least tolerant of losing a copy. Missense variants: 204 observed, 231.83 expected, observed/expected ratio (o/e) 0.88, 90% interval 0.78 to 0.99. Synonymous variants: 88 observed, 97.65 expected, observed/expected ratio (o/e) 0.9, 90% interval 0.76 to 1.08.
Homologues: Orthologues: chimpanzee C15H15orf62 (100% identical), macaque C7H15orf62 (98% identical), pig C15orf62 (87% identical), mouse Gm14137 (86% identical), rat C3h15orf62 (86% identical), rabbit C15orf62 (86% identical). Paralogues in human: CDC42EP1 (24% identical), CDC42EP4 (22% identical), CDC42EP3 (19% identical), CDC42EP2 (18% identical), CDC42EP5 (14% identical).